MITF (melanocyte inducing transcription factor)
Diseases named in the same sentence as MITF in open-access papers (continued):
Sharing a sentence is not in itself a finding about the gene and the disease.
melanoma (continued). "A significant proportion of established human melanoma cell lines express IL32, with its expression being highly correlated with a dedifferentiation genetic signature (high AXL/low MITF)." (PMID 30953519, 2019). "We selected these three melanoma cell lines to observe the parallel impact of TNFα and IFNγ on IL32 and the melanoma differentiation state because they exhibited a low AXL/high MITF differentiated genetic signature." (PMID 30953519, 2019). "To characterize which genes are mainly bound by MITF in melanocytes and melanoma cells, we analysed previously published MITF ChIP sequencing data from primary human melanocytes (NHEM) and from two human melanoma cell lines; COLO829 and 501mel25,27." (PMID 30705290, 2019). "Here we identified MITF, the MET receptor as well as several members of the secretory pathway as being regulated by SR-BI in human melanoma cells." (PMID 30823658, 2019). "In melanoma cell lines, miR‐182 was found upregulated and its overexpression promoted metastasis by repressing FOXO3 and MITF." (PMID 30499222, 2019). "We then used a mass spectrometry approach to interrogate the metabolite profile of the MITF‐high, non‐invasive melanoma cell line IGR37, and the IGR39 cell line derived from the same patient that is MITF‐low, invasive, and exhibits a pseudo‐hypoxic signature." (PMID 31207090, 2019). "In melanoma cells that are present in a NOTCH ligand-free microenvironment, the transcription factor MITF represses the miR-222/221 promoter." (PMID 30866509, 2019). "In melanoma, macrophage-derived TNFα is a key factor responsible for the resistance to MAPK inhibitors, acting via MITF, having the capacity to regulate survival and anti-apoptotic genes." (PMID 31652660, 2019). "Studies have confirmed that miR182 is highly expressed in melanoma, colon cancer, and lung cancer and can promote cell migration and invasion by inhibiting FOXO3 and MITF." (PMID 31885738, 2019). "Taken together, these data suggest that MITF knockdown results in decreased global starvation-induced autophagic degradation in both NHEM melanocytes and SkMel28 melanoma cells." (PMID 30705290, 2019). "Our results suggest that MITF and the related factors TFEB and TFE3 have separate roles in regulating a starvation-induced autophagy response in melanoma." (PMID 30705290, 2019). "E-box and SOX motifs are recognized by the lineage-determining factors MITF and SOX10, respectively, which are essential for melanocyte development and differentiation, normal melanocyte function, and melanoma initiation and proliferation." (PMID 31399133, 2019). "Melanomas, which progress on MAPK inhibitor therapies, acquire this genetic signature of reduced MITF and RTK upregulation." (PMID 30953519, 2019). "Reflecting their cancer specific relevance, expression of MITF, PAX3, and BRN2 is significantly enriched in melanoma cell lines as seen in a panel covering >20 general cancer types." (PMID 30277012, 2019). "Significant elevation in MITF and MITF target gene expression was also observed in mouse B16F10 melanoma cells and xenografts in bovine GH transgenic (bGH) mice compared to wild-type littermates." (PMID 31547367, 2019). "Gene expression scatterplots of MITF and TYR vs. IL32 show that melanoma cells with high IL32 expression are typically dedifferentiated, whereas differentiated melanoma are associated with absent or lower levels of IL32." (PMID 30953519, 2019). "We found that MITF mRNA expression was considerably (p = 0.075) lower, while EGFR mRNA expression was significantly (p = 0.016) higher in fast migrating melanoma cells." (PMID 31514305, 2019). "Melanocyte-inducing transcription factor (MITF) is the master regulator of melanocyte and melanoma cell fate as well as the melanosomal machinery." (PMID 31547367, 2019). "The MITF and SOX10 transcription factors regulate the expression of genes important for melanoma proliferation, invasion and metastasis." (PMID 31881017, 2019).
melanoma (continued). "During melanoma development, BRAF induces expression of MITF in order to control tumour growth, but this regulation is inverted when BRAF is inhibited." (PMID 30277012, 2019). "The concordant expression of MITF and c-MYC transcripts was confirmed in a panel of genetically heterogeneous melanoma lines by RT-PCR." (PMID 30651597, 2019). "In the amelanotic melanoma SK-MEL-28, MITF protein levels were significantly elevated in presence of excess GH as well as doxorubicin but were again strongly suppressed following GHRKD." (PMID 31547367, 2019). "Using our preclinical model of patient-derived melanoma cells cultured in stem cell medium (SCM), we investigated effects of targeted drugs, vemurafenib and trametinib, on MITF level and expression of MITF-dependent pigmentation/differentiation genes." (PMID 31354817, 2019). "To strengthen our finding of SR-BI regulating MITF as well as MET, we made use of two published melanoma whole genome expression studies." (PMID 30823658, 2019). "Resveratrol is known to inhibit α-melanocyte-stimulating hormone (MSH) signaling in melanoma cells and to reduce the tyrosinases TRP-1, 2, and MITF." (PMID 30813264, 2019). "The concordant expression of MITF and GTF2H1 transcripts was confirmed in several genetically heterogeneous melanoma lines by RT-PCR." (PMID 30651597, 2019). "Ectopic expression of TYRO3 in the murine B16:F10 melanoma cell line was sufficient to increase MITF protein levels and resulted in increased nuclear localization of SOX10, a known regulator of MITF in melanoma." (PMID 30501104, 2018). "We observed a similar positive correlation between MITF and CDK2 in melanoma patients, where melanoma exhibited the greatest and most significant correlation (Pearson r = 0.6, Padj = 3.3 e−53) among the available cancers (Dataset EV6)." (PMID 29507054, 2018). "Inhibition of BRAF mutations using MAPK inhibitors suppresses glycolysis leading to temporarily suppression of melanoma growth, but also promotes metabolic switch to OXPHOS phenotype via induction of MITF and PGC1α expression." (PMID 30651927, 2018). "While PGC-1α is essential to support mitochondrial respiration and survival in MITF-expressing cells, PGC-1α can also block melanoma progression by at least two distinct mechanisms." (PMID 29629336, 2018). "In addition, five genes (FGF10, FGF2, MITF, PDGFC, and PDGFD) were involved in “Melanoma”, which might be associated with the two-end black pigmentation observed in BMX pigs, which differs from most Chinese domestic pigs with black coats (China National Commission of Animal Genetic Resources, 2011)." (PMID 29955027, 2018). "As example, a copy number analysis indicated the pathogenetic coexistence of MITF amplification and expression of a specific lncRNA (SAMMSON) in a subset of melanomas." (PMID 30218391, 2018). "In conclusion, our study demonstrated that finasteride inhibited melanogenesis in melanocytes and melanoma cells through the down-regulation of tyrosinase, TRP-1, MITF and adenylate cyclase expression." (PMID 29397551, 2018). "We found that PAX3 and YAP interact in melanoma cells and that depletion of YAP using small interfering RNA (siRNAs) results in decreased MITF mRNA expression in cells cultured on >1 GPa collagen." (PMID 29545604, 2018). "The scenario of genetic alterations contributing to melanoma gene signature was completed by somatic CNVs, such as gene amplifications in CCND1, CDK4, KIT, MITF, and TERT as well as gene deletions in CDKN2A and PTEN." (PMID 30218391, 2018). "The results of western bolt assay showed thatECPS suppressed the expression of TRP-1, tyrosinase, and MITF in B16F10 cells andimplied that ECPS decreased melanogenesis by down-regulating tyrosinase, MITF, andTRP-1 expression in B16F10 melanoma cells." (PMID 29846408, 2018).
melanoma (continued). "Studies have shown that low level of endogenous MITF activity is oncogenic with BRAF (V600E), which also promotes melanoma progression." (PMID 30544544, 2018). "It has been reported that MITF regulates proliferation and apoptosis through CDK2 and BCL2 in melanoma cells." (PMID 29885053, 2018). "In differentiated melanocytes, TGFβ can reduce MITF through the suppression of PAX3, and we have recently shown that this regulatory link is preserved in melanoma cells." (PMID 29545604, 2018). "It has also been shown that BRAF inhibitor resistance can be mediated by regulatory escape of the transcription factor MITF from the MAPK pathway, where MITF overexpression itself conferred resistance in several melanoma cell lines." (PMID 30349559, 2018). "The investigators examined the heterogeneity of the melanoma phenotypes upon treatment with a BRAF inhibitor, using MITF as readout." (PMID 28694322, 2017). "Previously, the influence of aromatic-turmerone on inhibiting melanogenesis was suppressed by CREB activation, and expression of MITF, tyrosinase, TRP-1, and TRP-2 in B16F10 melanoma cells." (PMID 29019940, 2017). "Results showed that miR-26a mimics remarkably reduced the expressions of MITF and MAP4K3 in both SKMEL-28 and WM1552C melanoma cell lines." (PMID 28698805, 2017). "The trend for Melanoma antigen recognized by T-cells 1 (MART1) was quite similar to MITF, but there was a tendency that MART1+ cells appeared further down in the feather follicle in B0/N or B2/W chicken compared to wild-type." (PMID 28388616, 2017). "Melanomas of a “MITF‐high” phenotype usually respond well to BRAF inhibitor therapy, but these melanomas also contain subpopulations of the de novo resistance “AXL‐high” phenotype." (PMID 28606996, 2017). "We therefore investigated the effects of MITF and BRN2 expression in melanoma growth and metastasis." (PMID 28883623, 2017). "A candidate regulator of MITF levels in cancer stem cells is represented by the transcription factor BRN-2, which is frequently overexpressed in melanoma cells and represses MITF transcription." (PMID 29156643, 2017). "Our data highlights the importance of both MITF- and BRN2-expressing cells within the population in the growth and development of melanoma metastasis." (PMID 28883623, 2017). "Together, our data strongly suggest that glucose deprivation suppresses MITF expression through ROS induced ATF4 up-regulation, which in turn results in reduced melanoma cell proliferation." (PMID 28380427, 2017). "Theinterplay between MITF and BRG1 thus plays an essential role intranscription regulation in melanoma." (PMID 28521512, 2017). "Furthermore oxidative stress has previously been linked to downregulation of melanocyte differentiation markers, therefore we decided to study if ROS could be triggering glucose restriction-mediated inhibition of melanoma proliferation in a MITF dependent manner." (PMID 28380427, 2017). "B16F10 melanoma cells were exposed to various concentrations of 10-HDA (0.1, 0.5 and 1 mM), resulting in the down regulation of MITF expression by 10-HAD." (PMID 28793915, 2017). "This was seen also in other melanoma biopsies (Fig EV1A) and is entirely in line with single‐cell analysis data from MITF‐high melanomas." (PMID 28606996, 2017). "With this in mind, and to improve our understanding of the complexity of MITF‐high melanomas in the context of MAPK inhibitor resistance, we set out to analyse the dynamics of individual MITF‐expressing subpopulations during treatment with BRAF inhibitor." (PMID 28606996, 2017). "To corroborate our result, we also compared basal values of PAX3d, MITF-m and TGFB2 obtained in recurrence-free patients to those observed six months before melanoma relapse in subjects with a disease progression." (PMID 29156734, 2017). "Recent reports have suggested that melanoma cells switch back to the embryogenetic program initiated during neural crest formation by means of several factors as PAX3 and MITF." (PMID 29156734, 2017).
melanoma (continued). "Nevertheless, similar to what is seen in MITF‐high cells, conditioned medium from BRAF inhibitor pre‐treated melanoma cells profoundly protects AXL‐high cells from the growth inhibitory effect of BRAF inhibition." (PMID 28606996, 2017). "We assessed if MITF and BRN2 expression is required for primary melanoma tumor growth using mouse xenograft studies." (PMID 28883623, 2017). "Western blot analysis showed the expression level of both MITF and BRN2 in a panel of BRAFV600E mutant metastatic melanoma cell lines." (PMID 28883623, 2017). "Pear fruit and its constituent PCA effectively inhibit cellular tyrosinase activity and expression through cAMP/CREB/MITF-mediated mechanism, which contributes to reduction in α-MSH-stimulated melanogenesis in mouse and human melanoma." (PMID 28825660, 2017). "We found that in the context of glucose deprivation in melanoma, ATF4 negatively regulates the CRE of the MITF promoter." (PMID 28380427, 2017). "The effect of BRN2, MITF and NFIB over-expression in melanoma cell invasiveness was then determined using spheroids embedded in a collagen matrix, with invasion monitored at 24 h time points over a 72 h period." (PMID 28119061, 2017). "In line with our previous findings that MITF is up‐regulated on treatment, we found that EDN1 as well as EDNRB expression increased in melanomas of patients (n = 22) on treatment." (PMID 28606996, 2017). "The suppressor function of SKI is maintained in melanoma, where its overexpression led to a reduction and its depletion to an increase in PAX3 and MITF expression." (PMID 26977879, 2016). "MITF regulation by SOX5 has only been shown in murine cells so far and hence we were interested in the regulatory effect of SOX5 on MITF in human melanoma cells and tumors, and its regulatory effect in combination with SOX10." (PMID 26927636, 2016). "Nelfinavir efficiently suppressed PAX3 and MITF expression in a panel of BRAF mutant melanoma cells and reduced the GI50 for the MEK inhibitor selumetinib in drug-tolerant A375 melanoma cells (A375-T) by ∼60-fold, comparable with the GI50 in sensitive cells." (PMID 26977879, 2016). "In melanoma, SOX10 functions both independently and in cooperation with MITF to promote more differentiated and/or proliferative cellular states." (PMID 27852308, 2016). "We observed a similar effect in human melanoma cells: A double knockdown of SOX5 and SOX10 partially rescued MITF expression compared to a single knockdown of SOX10." (PMID 26927636, 2016). "To investigate the relationship between SOX10, MITF, FOXD3, ERBB3 and NRG1 in patient samples, we utilized The Cancer Genome Atlas (TCGA, SKCM), which contains a set of 474 melanoma patient samples." (PMID 27391157, 2016). "Because MITF is crucial for the survival of the melanocyte lineage, we argued that it would also be relevant for NRAS mutant melanoma cell survival." (PMID 26977879, 2016). "In all three tested melanoma cell lines (MaMel-61e, MaMel-122 and MaMel-86b) the knockdown of SOX5 resulted in significantly increased MITF levels compared to cells transfected with control siRNA." (PMID 26927636, 2016). "We also assessed melanoma cell survival in response to the drug library and set a threshold at the effect on survival induced by RNAi-mediated depletion of PAX3 or MITF, respectively." (PMID 26977879, 2016). "It was previously reported that CREB-binding protein (CBP) is a transcriptional coactivator of GLI, and the MITF and GLI2 genes were found to be inversely expressed in various melanoma cell lines." (PMID 27941997, 2016). "Five pathways wereenriched for genes in the module d-1 (MAPK1, MITF,RAF1, JAK1, and STAT3):pancreatic cancer (P=5.47E-04), melanoma (P=8.52E-03), melanogenesis (P=1.48E-02),acute myeloid leukemia (P=7.67E-03), and cancer pathways (P=3.69E-03)." (PMID 26840709, 2016). "The specific regulatory pathways affected by Lunasin to effect MITF and NANOG expression in melanoma ALDHhigh cells remain to be identified." (PMID 27566591, 2016).
melanoma (continued). "We confirmed experimentally that SOX5 and SOX10 have an effect on MITF expression levels in melanoma cell lines; SOX5 down-regulation increases MITF expression, hinting at an inhibitory effect, while vice versa, SOX10 down-regulation led to MITF up-regulation." (PMID 26927636, 2016). "In fact, in melanomas, hotspot regions or amplification of KIT, PIK3CA, MITF and CTLA4 are often analyzed." (PMID 26863566, 2016). "We compared basal mRNA expression levels of SOX10, MITF, FOXD3, and ERBB3 in immortalized melanocytes, and in a panel of melanomas spanning various genetic backgrounds." (PMID 27391157, 2016). "Several groups demonstrated that MITF directly regulates the expression of TRPM1 in vitro and in vivo during melanoma progression." (PMID 25710007, 2015). "The precise relationship and the interplay between PAX3, MITF and BRN2 in melanocytes and melanoma cells needs to be further investigated." (PMID 25880082, 2015). "Melanoma cells show high expression of CRD-BP (coding region determinant-binding protein), an mRNA-binding protein that has been found to stabilize MITF transcript." (PMID 25433395, 2015). "This not only emphasizes the relevance of the BRAF‐MITF link, but also confirms that BRAFV600E co‐operates with appropriate MITF levels in driving melanoma initiation." (PMID 25818589, 2015). "In summary, in order to fully dissect the regulation of MITF by BRN2, future analyses need to consider the genetic and signalling background of melanoma cells." (PMID 25818589, 2015). "Genes upregulated in this cluster include known markers of the melanocyte lineage and melanoma such as SOX10, MITF and PAX3." (PMID 25865119, 2015). "No mutations have been found in the putative miR-137-binding sites in the MITF mRNA 3′-UTR, however, miR-137 possesses a 15-bp tandem repeat in the pre-miR-137 sequence that alters the processing and function of miR-137 in melanoma cell lines." (PMID 25433395, 2015). "To further discern the roles of PAX3 in melanocyte and melanoma cells, we have analysed the correlation between PAX3 and MITF and BRN2." (PMID 25880082, 2015). "In melanoma, the upregulation of MITF can regulate tissue-dependent regulation of CDK2 (cyclin-dependent kinase 2), which plays important role in melanoma proliferation." (PMID 26393652, 2015). "Next, we confirmed these findings by qRT–PCR for the TNF-α responsive genes IL1B and IL6 using independent MITF siRNAs in MZ7 and two other MITFhigh melanoma cell lines, Ma-Mel-15 (MM15) and Ma-Mel-27 (MM27), respectively." (PMID 26530832, 2015). "Examination of publically available gene expression data on 120 melanoma cell lines demonstrated a consistent positive correlation between CITED1 and MITF expression (r = 0.6543)." (PMID 25755924, 2015). "It has been evidenced that melanoma cell lines with high levels of MITF (MITFhigh) were sensitive to either BRAFV600E or MEK inhibition, whereas cells with low MITF levels (MITFlow) displayed intrinsic resistance against the same drugs." (PMID 26322273, 2015). "We have assessed the expression of PAX3, MITF and BRN2 in two melanocyte cultures (NHEM-n and NHEM-a) and two melanoma cell lines (WM115 and M14) by RT-qPCR and western blot." (PMID 25880082, 2015). "Receptor tyrosine kinase expression/activation and gene expression analysis indicate that MITF drives the same down-stream pathways in CCS and in melanoma, and that PDGFRβ and c-Met are expressed by CCS." (PMID 25880253, 2015). "It appears that these other factors are stronger activators of the MITF promoter, as for instance in a panel of 88 short‐term melanoma cultures, high MITF RNA expression was found in a ‘low MAPK gene set’, but MITF expression was low in a ‘high MAPK gene set’." (PMID 25818589, 2015). "In this context, it is intriguing that in melanoma cells, BRAF suppresses FOXD3, which would allow MITF expression to prevail." (PMID 25818589, 2015).